KRTAP5-5 (keratin associated protein 5-5)
Description:
In the hair cortex, hair keratin intermediate filaments are embedded in an interfilamentous matrix, consisting of hair keratin-associated protein (KRTAP), which are essential for the formation of a rigid and resistant hair shaft through their extensive disulfide bond cross-linking with abundant cysteine residues of hair keratins. The matrix proteins include the high-sulfur and high-glycine-tyrosine keratins.
Synonyms: KRTAP5-11; KRTAP5.5
Tractability: No criterion of Open Targets' tractability assessment is met for any kind of drug.
Gene: Protein-coding gene on chromosome 11 (1,629,775 to 1,630,930, forward strand). Ensembl gene ENSG00000185940.
Pathways (Reactome):
Developmental Biology: Keratinization
Gene Ontology:
Cellular component: cytosol
Genetic constraint (gnomAD): Loss-of-function variants: 1 observed, 3.16 expected, observed/expected ratio (o/e) 0.32, 90% interval 0.11 to 1.42. That is too few expected variants to judge how well the gene tolerates losing a copy. Missense variants: 127 observed, 243.16 expected, observed/expected ratio (o/e) 0.52, 90% interval 0.45 to 0.61. Synonymous variants: 76 observed, 95.79 expected, observed/expected ratio (o/e) 0.79, 90% interval 0.66 to 0.96.
Homologues: Paralogues in human: KRTAP5-2 (63% identical), KRTAP5-8 (62% identical), KRTAP5-6 (49% identical), KRTAP4-6 (30% identical), KRTAP4-11 (30% identical), KRTAP4-12 (30% identical), KRTAP4-3 (29% identical), KRTAP10-7 (28% identical), KRTAP10-6 (27% identical), KRTAP4-5 (27% identical), KRTAP4-9 (27% identical), KRTAP10-9 (27% identical), and 35 more.
Diseases named in the same sentence as KRTAP5-5 in open-access papers:
KRTAP5-5 is named in the same sentence as 3 diseases in open-access papers, as found by Europe PMC text mining. Sharing a sentence is not in itself a finding about the gene and the disease. The quoted sentences say what the papers report.
mammary cancer (1 paper, 2023). "A genome-wide search for proteins linked to mammary cancer found KRTAP5-5 to be a regulator of cytoskeletal function that modulates cell motility and thus can lead to vascular invasion." (PMID 36941546, 2023).
cancer (1 paper, 2017). A tumor composed of atypical neoplastic, often pleomorphic cells that invade other tissues. "KRTAP5-5 is an oncogene regulating cancer cell motility and vascular invasion." (PMID 29262625, 2017).
KRTAP5-5 also shares sentences with these, for which no sentence is quoted: metastatic cancer (1 paper).